SEC13 (SEC13 homolog, nuclear pore and COPII component)
Description:
Functions as a component of the nuclear pore complex (NPC) and the COPII coat. At the endoplasmic reticulum, SEC13 is involved in the biogenesis of COPII-coated vesicles. Required for the exit of adipsin (CFD/ADN), an adipocyte-secreted protein from the endoplasmic reticulum (By similarity). As a component of the GATOR2 complex, functions as an activator of the amino acid-sensing branch of the mTORC1 signaling pathway. The GATOR2 complex indirectly activates mTORC1 through the inhibition of the GATOR1 subcomplex. GATOR2 probably acts as an E3 ubiquitin-protein ligase toward GATOR1. In the presence of abundant amino acids, the GATOR2 complex mediates ubiquitination of the NPRL2 core component of the GATOR1 complex, leading to GATOR1 inactivation. In the absence of amino acids, GATOR2 is inhibited, activating the GATOR1 complex. Within the GATOR2 complex, SEC13 and SEH1L are required to stabilize the complex.
Synonyms: D3S1231E; SEC13L1; SEC13R; npp-20
Tractability: Small molecule: it has a high-quality binding pocket. Antibody: UniProt places it where antibodies can reach, with high confidence. PROTAC: ubiquitination databases record sites on it; its protein half-life has been measured.
Gene: Protein-coding gene on chromosome 3 (10,293,131 to 10,321,123, reverse strand). Ensembl gene ENSG00000157020.
Subcellular location: Cytoplasmic vesicle, COPII-coated vesicle membrane; Endoplasmic reticulum membrane; Nucleus, nuclear pore complex; Lysosome membrane
Subcellular location (Human Protein Atlas): Nucleoplasm; Vesicles
Pathways (Reactome):
Disease: Defective TPR may confer susceptibility towards thyroid papillary carcinoma (TPC); HCMV Early Events; HCMV Late Events; NEP/NS2 Interacts with the Cellular Export Machinery; NS1 Mediated Effects on Host Pathways; Nuclear import of Rev protein; Rev-mediated nuclear export of HIV RNA; SARS-CoV-2 activates/modulates innate and adaptive immune responses; Transport of Ribonucleoproteins into the Host Nucleus; Viral Messenger RNA Synthesis; Vpr-mediated nuclear import of PICs
Cell Cycle: Amplification of signal from unattached kinetochores via a MAD2 inhibitory signal; EML4 and NUDC in mitotic spindle formation; Mitotic Prometaphase; Nuclear Pore Complex (NPC) Disassembly; Postmitotic nuclear pore complex (NPC) reformation; Resolution of Sister Chromatid Cohesion; Separation of Sister Chromatids
Metabolism of RNA: Transport of Mature mRNA Derived from an Intronless Transcript; Transport of Mature mRNA derived from an Intron-Containing Transcript; Transport of the SLBP Dependant Mature mRNA; Transport of the SLBP independent Mature mRNA; snRNP Assembly; tRNA processing in the nucleus
Metabolism of proteins: SUMOylation of DNA damage response and repair proteins; SUMOylation of DNA replication proteins; SUMOylation of RNA binding proteins; SUMOylation of SUMOylation proteins; SUMOylation of chromatin organization proteins; SUMOylation of ubiquitinylation proteins
Metabolism: IP3 and IP4 transport between cytosol and nucleus; IP6 and IP7 transport between cytosol and nucleus; IPs transport between nucleus and cytosol; Regulation of Glucokinase by Glucokinase Regulatory Protein
Immune System: Antigen Presentation: Folding, assembly and peptide loading of class I MHC; ISG15 antiviral mechanism; MHC class II antigen presentation
Cellular responses to stimuli: Amino acids regulate mTORC1; Regulation of HSF1-mediated heat shock response
Signal Transduction: RHO GTPases Activate Formins
and 1 more pathways
Gene Ontology:
Molecular function: identical protein binding; protein binding; structural molecule activity
Biological process: cellular response to nutrient levels; COPII-coated vesicle cargo loading; positive regulation of TORC1 signaling; COPII-coated vesicle budding; intracellular protein transport; negative regulation of TORC1 signaling; nucleocytoplasmic transport; positive regulation of ER to Golgi vesicle-mediated transport; positive regulation of TOR signaling; protein import into nucleus; endoplasmic reticulum to Golgi vesicle-mediated transport
Cellular component: COPII vesicle coat; endoplasmic reticulum membrane; extracellular exosome; GATOR2 complex; kinetochore; lysosomal membrane; nuclear envelope; nuclear pore outer ring; nucleoplasm; cytosol; endoplasmic reticulum; ER to Golgi transport vesicle membrane; nuclear pore
Genetic constraint (gnomAD): Loss-of-function variants: 25 observed, 47.27 expected, observed/expected ratio (o/e) 0.53, 90% interval 0.38 to 0.74. The upper end of that interval is the gene's LOEUF score, 0.74, which puts it in group 3 of 6, group 1 being the genes least tolerant of losing a copy. Missense variants: 370 observed, 412.61 expected, observed/expected ratio (o/e) 0.9, 90% interval 0.82 to 0.98. Synonymous variants: 144 observed, 165.97 expected, observed/expected ratio (o/e) 0.87, 90% interval 0.76 to 1.
Homologues: Orthologues: chimpanzee SEC13 (99% identical), macaque SEC13 (99% identical), dog SEC13 (98% identical), rat Sec13 (97% identical), mouse Sec13 (97% identical), guinea pig SEC13 (95% identical), rabbit SEC13 (95% identical), pig SEC13 (94% identical), tropical clawed frog sec13 (89% identical), zebrafish sec13 (87% identical), Drosophila melanogaster Sec13 (57% identical), Caenorhabditis elegans npp-20 (41% identical). Paralogues in human: SEH1L (33% identical).
Diseases named in the same sentence as SEC13 in open-access papers:
SEC13 is named in the same sentence as 17 diseases in open-access papers, as found by Europe PMC text mining. Sharing a sentence is not in itself a finding about the gene and the disease. The quoted sentences say what the papers report.
glioma (2 papers, 2024 to 2025). A benign or malignant brain and spinal cord tumor that arises from glial cells (astrocytes, oligodendrocytes, ependymal cells). "Here, we identified a novel ER stress and UPR-driven gene signature, ESURATAG, composed of six genes (DERL2, RPN2, SEC13, SEC61A1, SEC61B, and STT3A) that are significantly upregulated in gliomas from older patients and strongly linked to tumor aggressiveness." (PMID 40718795, 2025). "Six out of eight genes namely, DERL2, RPN2, SEC13, SEC61A1, SEC61B and STT3A were interacting, and were combined into ER stress and UPR-driven aging-related tumor aggressiveness in glioma (ESURATAG) gene signature." (PMID 40718795, 2025). "We identified ER stress and UPR as key aging-related mechanism behind tumor aggressiveness in gliomas, and developed a six gene “ER Stress and UPR-driven Aging-related Tumor Aggressiveness in Glioma” (ESURATAG) gene signature, comprising DERL2, RPN2, SEC13, SEC61A1, SEC61B, and STT3A." (PMID 40718795, 2025).
HIV-1 infection (2 papers, 2018 to 2024). The type species of lentivirus and the etiologic agent of acquired immunodeficiency syndrome (AIDS). "Furthermore, Sec13 depletion was found to inhibit HIV-1 infection by reducing HIV integration." (PMID 38038453, 2024). "In addition, silencing of SEC13 inhibits HIV-1 infection by reducing HIV integration." (PMID 38038453, 2024). "Moreover, some Nup depletions (SEH1, NUP85, NUP160, SEC13, NUP98, NUP107, ELYS/ACHTF1, NUP93, NUP205, NUP88, and NUP214) that reduced both HIV-1 infection and MX2 activity in dividing HeLa cells, affected MX2 activity but not HIV-1 infection in non-dividing HeLa cells." (PMID 30084827, 2018).
influenza (2 papers, 2022 to 2024). An acute viral infection of the respiratory tract, occurring in isolated cases, in epidemics, or in pandemics; it is caused by serologically different strains of viruses (influenzaviruses) designated A, B, and C, has a 3-day incubation period, and usually lasts for 3 to 10 days. "Influenza-infected cells were immunostained for Sec13 and NS1 to show infection efficiency and NS1-specific localization." (PMID 38038453, 2024). "We first confirmed the association of Sec13 with NS1 by performing immunostaining for influenza virus and Sec13 in influenza-infected cells." (PMID 38038453, 2024). "In the present study, we identified and validated Sec13 a novel host interactor of influenza." (PMID 38038453, 2024). "Moreover, the colocalization of NS1 and Sec13 were correlated at several time points of infection, indicating the function of Sec13 during influenza infection." (PMID 38038453, 2024). "Hence, Sec13 has been identified as a novel host interactor and plays an essential role in the ER-to-Golgi pathway during influenza infection." (PMID 38038453, 2024). "Specifically, Sec13 has a functional role in influenza replication and virulence." (PMID 38038453, 2024). "Given that the RNA binding domain of NS1 could also be docked with Sec13, this could be related to the pathogenicity of different influenza strains." (PMID 38038453, 2024). "This would highlight the key role Sec13 involved in viral replication which may extend into influenza." (PMID 38038453, 2024). "Sec13 was identified as a novel host interactor of influenza." (PMID 38038453, 2024). "Sec13 was also identified as a host interactor of influenza in a CRISPR knockout screen." (PMID 38038453, 2024). "Hence, we propose that the ER-to-Golgi transport is an important pathway of viral replication and viral export, and specifically, Sec13 has a functional role in influenza replication and virulence." (PMID 38038453, 2024). "Sec13 was overexpressed to study the role of Sec13 in influenza infection." (PMID 38038453, 2024). "Indeed, Sec13 was shown to colocalize with influenza NS1 protein after infection." (PMID 38038453, 2024). "Therefore, the role and function of Sec13 in the influenza life cycle and were investigated." (PMID 38038453, 2024). "A member of the COPII complex, Sec13, was previously identified in a CRIPSR knockout screen to reduce influenza replication." (PMID 35531276, 2022). "We observed that overall Sec13 levels do not change during influenza infection and with different influenza strains." (PMID 38038453, 2024). "The decrease in NS1 and Sec13 overlap may be due to the change in NS1 and Sec13 localization during influenza." (PMID 38038453, 2024). "A yeast screen was performed to identify novel host factors of influenza and it was observed that NS1 colocalized in the ER to Golgi vesicle (Sec13) but not late Golgi in yeast." (PMID 38038453, 2024).
colon cancer (1 paper, 2024). "However, the gene and protein expression of SEC13 is dramatically increased in colon cancer (CC) patients, which may be related to its glycolytic function, suggesting that SEC13 has opposite effects in different cancer backgrounds." (PMID 39080077, 2024).
gastric cancer (1 paper, 2022). A primary or metastatic malignant neoplasm involving the stomach. "SMAD7, HIF-1α gene and HIF-1α protein may be jointly involved in tumor development and prognosis (act as oncogenic factors), while SEC13, GHRL, and lncRNA GHRLOS may act as tumor suppressor factors and thus could be considered as novel therapeutic targets for gastric cancer." (PMID 35449150, 2022).
malaria (1 paper, 2024). Malaria is a serious and sometimes fatal disease caused by a parasite that commonly infects a certain type of mosquito which feeds on humans. "Eleven Nups are currently known in the rodent malaria model P. berghei: Sec13, five FG Nups, and five novel Nups identified using Nup313 as bait in proximal labeling assays (15, –, 17)." (PMID 39526784, 2024). "Similarly, partial knockdown of SEC13 in human malaria parasites slows their growth in the blood stage, and a C-terminal proline-enriched sequence in SEC13 is required for parasite growth in mouse models." (PMID 39526784, 2024).
Obesity (1 paper, 2023). Accumulation of substantial excess body fat. "A gene ontology analysis showed some proteins related to obesity in the “extracellular exosome” term among differentially identified proteins in the gene ontology cellular component terms Prelp, Sec13, and Sod2." (PMID 36674516, 2023). "The selected proteins Prelp, Sec13, and Sod2 identified by the proteomic analysis were chosen for their relevant role in obesity and different abundance between groups." (PMID 36674516, 2023).
parasitemia (1 paper, 2014). "Exposure of parasite cultures to increasing concentrations of Sec13-PNA resulted in clear dose dependent inhibition in parasites' proliferation, while no such decrease in parasitemia was found in those that were treated with Scr-Sec13-PNA." (PMID 24466246, 2014).
viral infections (1 paper, 2024). "Sec13 has been identified as an essential host interactor in viral infections such as brome mosaic virus (BMV) in plants and HIV." (PMID 38038453, 2024). "Sec13 has been previously identified as an essential host interactor in human HIV and plant BMV viral infections." (PMID 38038453, 2024).
cancer (5 papers, 2016 to 2024). A tumor composed of atypical neoplastic, often pleomorphic cells that invade other tissues. "SMAD7, HIF-1α gene, and HIF-1α protein may be jointly implicated in cancer development and prognosis, while SEC13, GHRL, and lncRNA GHRLOS may act as tumor suppressors." (PMID 35449150, 2022). "However, the specific roles of SEC13, ALG1, FAM162A, GALK1, and XYLT2 in cancer remain unclear." (PMID 35963622, 2022). "This study confirmed decrease in SEC13 expression with all cancer stages (II, III, IV); while SMAD7 tended to be especially highly expressed in GC patients with stage IV, which could explain the significant negative correlation between SEC13 and SMAD7." (PMID 35449150, 2022).
infection (4 papers, 2015 to 2025). The state of being infected such as from the introduction of a foreign agent such as serum, vaccine, antigenic substance or organism. "Colocalization of NS1 and Sec13 were correlated at several time points of infection and inhibiting the ER-to-Golgi transport and silencing Sec13 decreased viral titers, whereas overexpressing Sec13 increased viral titers." (PMID 38038453, 2024). "At 16 hpi, representing a late infection time point toward the end of virus replication cycle, Sec13 was observed to localize more with the ER and COPII complex." (PMID 38038453, 2024). "After 8 h of infection, less Sec13 was observed at the COPII vesicles, while more Sec13 were found in the cis-Golgi compared to uninfected cells." (PMID 38038453, 2024). "We could consistently achieve a partial reduction in PsV infection with Sec13 depletion, achieving approximately 40% reduction in infection over nine experiments." (PMID 40431628, 2025). "The similar trafficking of Sec13 and NS1 in the Golgi to ER at 8 and 16 h, respectively, and that NS1 and Sec13 interac could imply that NS1 binds to Sec13 during this redistribution of NS1 from the Golgi to the ER at later time points of infection." (PMID 38038453, 2024). "This accumulation may be due to a redistribution of Sec13 to the Golgi via COPII during early infection." (PMID 38038453, 2024). "Sec13 was in the cytoplasm throughout infection, localized outside the nucleus with NS1 at 8 h post-infection (hpi)." (PMID 38038453, 2024). "As Sec13 is a member of the nuclear pore complex and coat protein complex II (COPII) vesicles, localization of both Sec13 and non-structural protein 1 (NS1) in the nucleus, endoplasmic reticulum (ER), COPII vesicles (ER-to-Golgi transport), and Golgi was studied during infection." (PMID 38038453, 2024).
tumor (3 papers, 2022 to 2025). "In GC patients, the expression of SEC13 is significantly decreased and negatively correlated with tumor stage, suggesting that SEC13 may act as a tumor suppressor in GC." (PMID 39080077, 2024).
SEC13 also shares sentences with these, for which no sentence is quoted: Autoimmunity (1 paper); brain tumour (1); Intellectual disability (1); malignant glioma (1); retinal degeneration (1).